RNU6-311P (RNA, U6 small nuclear 311, pseudogene)
Gene: Small nuclear RNA gene on chromosome 11 (78,579,255 to 78,579,356, reverse strand). Ensembl gene ENSG00000252033.
Homologues: Orthologues: chimpanzee U6 (99% identical), macaque U6 (92% identical). Paralogues in human: RNU6-642P (81% identical), RNU6-1020P (80% identical), RNU6-1164P (80% identical), RNU6-1309P (80% identical), RNU6-24P (80% identical), RNU6-43P (80% identical), RNU6-560P (80% identical), RNU6-767P (80% identical), RNU6-1011P (79% identical), RNU6-1243P (79% identical), RNU6-189P (79% identical), RNU6-266P (79% identical), and 1287 more.